ACHE (acetylcholinesterase (Yt blood group))
Diseases named in the same sentence as ACHE in open-access papers (continued):
Sharing a sentence is not in itself a finding about the gene and the disease.
Obesity (26 papers, 2019 to 2025). Accumulation of substantial excess body fat. "Therefore, future developments with galantamine and other centrally acting AChE inhibitors in the treatment of patients with obesity-associated disorders may include assessing the potential benefit of these drugs on cognition." (PMID 31024226, 2019). "Coenzyme Q10 mitigates hippocampal neuronal damage and improves cognitive function in MSG-induced obesity, primarily through its antioxidant and AChE inhibitory properties." (PMID 40066120, 2024). "For this pharmacological validation, a panel of enzymes were chosen whereby α-amylase and α-glucosidase are used for DM type 2, AChE and BChE for AD, tyrosinase and elastase for cutaneous manifestations and pancreatic lipase for obesity." (PMID 35335362, 2022). "Cholinergic drugs, including α7nAChR agonists and acetylcholinesterase (AChE) inhibitors, have also been shown to be cognitive enhancers and to reduce inflammation and metabolic imbalances in obesity and in MetS." (PMID 34685507, 2021). "The majority of the main evidence includes oxidative-stress, inflammation, obesity, dysregulation of Apolipoprotein E (APOE), insulin degradation enzyme (IDE), Glucose Transporter type 4 (GLUT4), and Acetylcholinesterase (AChE), are linked to insulin resistance." (PMID 36092798, 2022). "The common targets of obesity, T2DM, and NAFLD are solute carrier family 6 member 4 (SLC6A4), acetylcholinesterase (ACHE), opioid receptor Mu 1 (OPRM1), and glycogen synthase kinase 3 beta (GSK3B)." (PMID 39575382, 2024). "Enzymes that are drug targets for NCDs include lipase (obesity), α-amylase and α-glucosidase (diabetes), angiotensin-converting enzyme (ACE) (hypertension) as well as acetylcholinesterase (AChE), butyrylcholinesterase (BChE) and β-secretase (BACE-1) (AD)." (PMID 34451608, 2021). "We also consider the potential benefit of enhancing cholinergic signaling by centrally acting AChE inhibitors and VNS for counteracting cognitive deterioration in obesity-driven conditions." (PMID 31024226, 2019). "This large body of preclinical evidence and the fact that both centrally acting AChE inhibitors and VNS are already in clinical use provide a rationale for expanding these approaches into clinical settings of obesity." (PMID 31024226, 2019). "Compared with their healthy counterparts, individuals with obesity showed a higher, albeit not significantly different AChE expression, unchanged BuChE levels and, similar to mouse tissues, significantly increased ChT1 mRNA expression." (PMID 38141849, 2024). "The extracts were also evaluated for in vitro antioxidant capacity, by complementary assays, and for enzymatic inhibitory properties toward enzymes related with the onset of AD (AChE and BuChE), T2DM (α-glucosidase), obesity/acne (lipase), and skin hyperpigmentation/food oxidation (tyrosinase)." (PMID 36903857, 2023). "Although the behavior of AChE in obesity has not always been consistent according to some studies and it seems to be dependent on the brain structure under study, there is a clear impact of diet-induced obesity on the brain functions regulated by the cholinergic system." (PMID 39199499, 2024). "In humans, obesity did not induce significant changes in omental AChE or BuChE mRNA expression." (PMID 38141849, 2024).
Hypertension (25 papers, 2015 to 2026). The presence of chronic increased pressure in the systemic arterial system. "The data on the inhibition of ACE and AChE activity and advanced glycation end-products (AGEs) formation are important against hypertension, Alzheimer-type dementia, and diabetic complications, respectively." (PMID 41155415, 2025). "In this context, it is also noteworthy that ATR1 blockade appears to reduce the cerebral levels and activity of AChE in rats with deoxycorticosterone acetate (DOCA)-salt induced experimental hypertension." (PMID 33672482, 2021). "However, acetylcholine, like adenosine also serve as a vasodilator in the cardiovascular system and hence, their continual breakdown as a result of increased activity of AChE could be implicated in pathogenesis of many cardiovascular diseases as well as hypertension." (PMID 29876111, 2018). "Erythrocyte AChE is considered a biomarker of essential hypertension, glaucoma, ALS, neurotoxicity, and pesticide poisoning and a diagnostic marker in Hirschsprung’s disease." (PMID 28885588, 2017). "Young, healthy carriers of this SNP express 40% higher brain AChE activity than others, potentially affecting the responsiveness to AD’s anti-AChE therapeutics, and show elevated trait anxiety, inflammation and hypertension." (PMID 27386172, 2015). "The associations between acute exposure to AChE inhibitor insecticide and pancreatic cancer were not statistically significant across age groups (p = 0.23) or among individuals with or without hypertension (p = 0.07)." (PMID 41149448, 2025). "Higher AChE enzyme activity in RBCs were verified in glaucoma, essential hypertension, and ALS, which are inflammatory vascular diseases characterized by a presence in the blood of high inflammatory molecule concentrations, reactive oxygen species, and reactive nitrogen species." (PMID 28885588, 2017). "Additionally, higher AChE activity has been observed in several diseases, such as lung cancer, glaucoma, ALS, Hirschsprung’s disease, pesticide poisoning, neurotoxicity, or essential hypertension." (PMID 38256241, 2024). "Ex vivo studies using blood samples obtained from patients suffering different diseases, namely Parkinson, essential hypertension, glaucoma, retinal vasculitis, amyotrophic lateral sclerosis (ALS), and Hirschsprung’s disease, have evidenced augmented levels of RBC AChE enzyme activity." (PMID 28885588, 2017).
glaucoma (21 papers, 2012 to 2025). Increased pressure in the eyeball due to obstruction of the outflow of aqueous humor. "These experimental findings confirm that substituted methoxy (-OCH3) and bromophenols may be used as leads for generating potent CAI and AChE inhibitors associated with some global disorders, including AD, epilepsy, and glaucoma." (PMID 36364255, 2022). "Discovery of novel inhibitors of AChE is important in developing new drug candidates for the treatment of AD, MG, and glaucoma as well new insecticidal drugs." (PMID 24381529, 2013). "Rosmarinic acid modulates pathways such as VEGF (vascular endothelial growth factor) and AChE (acetylcholinesterase) inhibitory pathways, potentially preventing hypoxia-induced angiogenesis and related complications in conditions like glaucoma." (PMID 40427431, 2025). "Additionally, we believe that these results may be useful for the synthesis of new hCA I and II isoenzymes, AChE and BChE inhibitors, and in the development of drugs for the treatment of some common and global diseases including edema, epilepsy, glaucoma, mountain sickness, and AD." (PMID 36986640, 2023).
Ataxia (20 papers, 2010 to 2023). Ataxia refers to impaired coordination of voluntary muscle movement. "The inhibition of AChE, one of the most important modes of action of VOCs, causes the accumulation of acetylcholine at the synapse site; the postsynaptic membrane is permanently stimulated, resulting in ataxia, loss of coordination in the nervous and neuromuscular systems and eventually death." (PMID 36616236, 2022). "Inhibition of AChE leads to accumulation of acetylcholine at nerve synapses, and thus permanent conduction of nerve impulses, ataxia, convulsions and death." (PMID 35250641, 2022). "Other essential oil constituents inhibit acetyl cholinesterase (AchE) resulting in ataxia, either by irreversible inhibitory effect or reversible competition for the enzyme’s active site." (PMID 28412962, 2017). "The current findings could further be explained in the light of Singh and Singh and Zibaee, who reported restlessness, paralysis, and ataxia in the target host, which ultimately imparted mortality due to the inhibition of AChE activities." (PMID 30096781, 2018). "We speculated that the synergy between chlorantraniliprole and M. anisopliae affected AChE activity, thus mitigating symptoms of paralysis and ataxia." (PMID 27328936, 2016). "Inhibition of AChE causes acetylcholine to accumulate at synapses, such that post-synaptic membranes remain in a state of permanent stimulation; the result is paralysis, ataxia, a general lack of coordination in the neuromuscular system and eventual death." (PMID 27328936, 2016). "The symptoms of toxic damage that were observed, expressed in breathing difficulty, initially rapid and then severely delayed, ataxia, lack of coordinated movements, tremor and tonic-clonic seizures, are characteristic of acetylcholine (ACh) neurotoxicity due to inhibition of AChE." (PMID 33806197, 2021). "AChE inhibition results in accumulation of acetylcholine at the nerve synapses, so that the postsynaptic membrane is in a state of permanent stimulation producing paralysis, ataxia, general lack of coordination in neuromuscular system, and eventual death." (PMID 21048864, 2010).
amyloid (19 papers, 2010 to 2026). "For instance, AChE activity has been mainly associated with the amyloid core of senile plaques in the brain of AD patients." (PMID 34207788, 2021). "The activity of AChE increases around the amyloid plaques and is believed to be caused by the direct action of Aβ on AChE." (PMID 34884789, 2021). "The main symptom (i.e., memory disturbances) is primarily caused by the destruction of cholinergic neurons, but β-amyloid accumulation and oxidative stress can also reduce acetylcholine synthesis by reducing choline acetyl transferase activity or increasing acetylcholinesterase (AChE) activity." (PMID 39135795, 2024). "Cholinergic dysfunction is a hallmark of Alzheimer's disease (AD), driven by elevated acetylcholinesterase (AChE) and butyrylcholinesterase (BChE) activity that depletes acetylcholine and contributes to amyloid pathology." (PMID 41590732, 2026). "Increased plasma AChE activity correlates with higher amyloid plaque burden across multiple cortical regions, suggesting a link between peripheral cholinergic activity and central amyloid pathology." (PMID 40709526, 2025). "As a novel and potent AChE inhibitor, our study demonstrates that inhibition of the enzyme AChE by XJP-1 treatment improves the amyloid-induced symptomatology in Drosophila, by reducing the number of amyloid plaques within the fruit fly CNS." (PMID 34276297, 2021). "Many lines of evidence suggest that both AChE and BChE, which are localized within Aβ plaques in the AD brain, are related to amyloid plaque formation and thus contribute to the neuropathology of the disease." (PMID 32867324, 2020). "Acetylcholinesterase (AChE), which is most widely known for the hydrolysis of the neurotransmitter acetylcholine, has a peripheral allosteric subsite responsible for amyloidosis in Alzheimer’s disease through interaction with amyloid β-peptide." (PMID 29873262, 2018). "Total AChE expression in the AD brain was reduced only to a minor extent, but AChE-R levels were drastically reduced to about 20% of control levels, supporting the notion that loss of this naturally rare variant may be involved with amyloid plaque development in the human brain as well." (PMID 23908786, 2010). "It has also been reported that AChE and BChE co-localize within the brain in amyloid plaques to form insoluble β-amyloid fibrils." (PMID 20550720, 2010). "Additionally, acetylcholinesterase (AChE) activity increases and deactivates acetylcholine in synaptic clefts in the vicinity of amyloid plaques." (PMID 37113145, 2023). "Moreover, PPE ameliorated spatial memory along with reduced amyloid plaque density and AchE activity." (PMID 36655111, 2023). "The conjugates could bind to the AChE peripheral anionic site and displace propidium, indicating their potential to block AChE-induced β-amyloid aggregation, thereby exerting a disease-modifying effect." (PMID 32867324, 2020). "Neurofibrillary tangles and amyloid plaques express AChE and BChE activity in AD." (PMID 20550720, 2010). "The authors reported that consumption of pomegranate peel extract resulted in reduced amyloid plaque density, increased brain-derived neurotrophic factor (BDNF) secretion and decreased acetylcholinesterase (AChE) activity." (PMID 36768185, 2023).
cognitive disorder (19 papers, 2014 to 2025). A disease affects cognitive processes. "Such action of excessive AChE may also link to other cognitive diseases, for example autism, because alterations in cholinergic activity and/or in neuroligin-neurexin association in the brain lead to autism spectrum disorders." (PMID 24594013, 2014).
lung carcinoma (17 papers, 2014 to 2025). "Case–control studies were conducted previously to relate (AChE) expression levels and activities in patients having several forms of lung cancers and they showed a significant decrease in AChE activity in such patients." (PMID 38429330, 2024). "Martínez-Moreno and coworkers showed a decrease in mRNA-T expression in human lung cancer compared with the other two mRNA types of AChE (H and R)." (PMID 37760598, 2023). "Many studies have reported earlier that the activity of AChE was decreased in lung cancer, likely leading to enhanced lung cancer growth." (PMID 36142659, 2022). "Decreased activity of AChE was reported in lung cancer, likely contributing to increased ACh levels, lung cancer tumor growth rate and aggressiveness, grim prognosis, and reduced survival chance." (PMID 36142659, 2022). "The regulation of AChE activity by small molecules has been investigated as a strategy for lung cancer therapy." (PMID 33917200, 2021). "The simple assumption is that small molecules, which increase activity of AChE in human lung cancer cells, will reduce the levels of ACh." (PMID 33917200, 2021). "Recently, a novel series of biscoumarin derivatives with AChE and butyrylcholinesterase inhibitory activities have been shown to inhibit the proliferation of A549 human lung carcinoma cells." (PMID 34500749, 2021). "On the other hand, acetylcholine has also been suggested to act as a growth factor for lung epithelial cells, which is supported by the fact that its levels are elevated in lung cancer while that of AChE is decreased." (PMID 34500749, 2021). "The activity of AChE was found to be reduced in lung cancer, likely contributing to increased acetylcholine levels, lung cancer growth and tumor aggressiveness, poor prognosis, and low survival rate." (PMID 32193421, 2020). "Several earlier reports showed that the activity of AChE was reduced in lung cancer, likely contributing to lung cancer growth." (PMID 32193421, 2020). "The cholinergic system comprising ACh and its synthesizing enzyme, choline acetyltransferase (ChAT), as well as its degrading enzyme, acetylcholinesterase (AChE), have been detected in several cancer entities, such as colon, liver and lung cancer." (PMID 33357230, 2020). "Using media from either A549 or H1299 lung cancer cells, we observed that more HN was bound to Aβ upon addition of ATP, while levels of AChE in a complex with Aβ were decreased by ATP addition to A549 cell media." (PMID 33145964, 2020). "The probe BF2-cur-Ben could successfully track AChE expression in PMA-induced apoptosis of lung cancer cells and its ability to monitor AChE in organisms was confirmed by detecting AChE activity in zebrafish." (PMID 38731452, 2024). "Furthermore, these probes focus mostly on AChE in brain cells or tissues and rarely monitor AChE in lung cancer cells." (PMID 38731452, 2024). "These probes can monitor the overexpression of AChE during apoptosis of lung cancer cells." (PMID 38731452, 2024). "Abnormal expression and structural alterations of AChE were observed in different tumors, as reduced activity may contribute to lung cancer growth." (PMID 37147356, 2023). "Subsequent studies have shown that lung cancer cell lines (as well as lung tissue) presented patterns of AChE dimers and monomers, pointing out that the variations in these two molecular forms could contribute to the survival of the tumors." (PMID 37760598, 2023). "In comparing two human lung cancer cells, we previously found lower levels of acetylcholinesterase (AChE) and intact amyloid-β40/42 (Aβ), and higher levels of mature brain-derived neurotrophic factor (mBDNF) in the media of H1299 cells as compared to A549 cell media." (PMID 36142659, 2022). "Indeed, it was demonstrated that the increased activity level of AChE suppresses proliferation, growth, and survival of human lung cancer." (PMID 33917200, 2021).
lung carcinoma (continued). "Accordingly, the decrease in the functional activity of AChE and butyrylcholinesterase (BChE) by using their inhibitor promoted the proliferation of human lung cancer cells by maximizing/increasing the level of the growth factor ACh using their inhibitor in human cancer tissue." (PMID 33917200, 2021). "In lung cancer, the AChE activity is reduced, and the level of acetylcholine (ACh) is increased." (PMID 33917200, 2021). "ATP, at concentrations (200 μm) chosen to be within the extracellular physiological concentrations previously found (> 100 μm) in the lung cancer cell lines used in this study, was found to weaken interactions between AChE and Aβ but strengthens those between Aβ and HN." (PMID 33145964, 2020). "Whether HN or AChE plays a role in regulating Aβ phosphorylation and/or aggregation in lung cancer cells is currently a focus of research investigation in our laboratory." (PMID 33145964, 2020). "Increased ACh was found in lung cancer tissues due to the abnormal expression of AChE." (PMID 25220382, 2014). "Abnormal expression of AChE has been observed in malignant grade III brain tumors, type IV glioma, lung cancer, retinoblastoma, squamous cell carcinoma, and human tumor cell lines of different tissue origin." (PMID 34500749, 2021).